IL1B (interleukin 1 beta)
Diseases named in the same sentence as IL1B in open-access papers (continued):
Sharing a sentence is not in itself a finding about the gene and the disease.
cancer (continued). "In this regard, it should be mentioned that IL-1β acts as an important effector of the oncogene-driven pathways linking inflammation to cancer." (PMID 32778144, 2020). "TAMs produce multiple growth factors and inflammatory cytokines (IL–1β, IL–6 and TNF–α), each associated with EMT in cancer cells." (PMID 32443890, 2020). "Inhibitor of IL-1β, Anakinra or Canakinumab, reduces metastasis and the number of cancer cells shed into the circulation." (PMID 33123472, 2020). "Production of IL-1β by cancer cells or neighboring cells can activate many molecular pathways that lead to cancer cell migration." (PMID 32635472, 2020). "Beyond regulating cancer appearance or progression, IL-1β can also influence anti-cancer treatments." (PMID 32635472, 2020). "NLRP3 and IL1B were upregulated in cancer tissue compared to normal, while IL6 expression was unaltered." (PMID 32630814, 2020). "Inflammasomal production of IL-1β reinforces the cancer stem cell phenotype and contributes to its invasive capacity and survival resiliency." (PMID 33613533, 2020). "A similar phenomenon during the adipocyte and cancer cell co-culture was observed for the pro-inflammatory cytokines IL-6, IL-1β, IL-8, and for the fatty acid-binding proteins (FABPs), which was found to promote homing, migration, and invasion of cancer cells." (PMID 32015297, 2020). "In murine cancer models, HMGB1 and S100B induce muscle wasting and this is associated with elaboration of IL-1β and IL-6." (PMID 33291708, 2020). "In mice, IL-1β involvement in cancer incidence was addressed, using IL-1β expression specifically in the pancreas, via the elastase promoter." (PMID 32635472, 2020). "Animal and cell culture studies showed that arsenic trioxide and other arsenic compounds inhibited NLRP3 inflammasome, caspase-1, and IL-1β inflammatory signaling, and played a major role in its anti-cancer effects." (PMID 32313131, 2020). "Targeting IL-1β with Canakinumab opened a new era in the use of selective anti-inflammatory therapies in cardiovascular diseases, but its potential in cancer prevention needs to be further explored." (PMID 33195486, 2020). "In summary, the IKKβ/NF-κB signaling pathway and the pro-inflammatory cytokines TNF-α, IL-1β, and IL-6 play important regulatory roles in the development of cancer pain." (PMID 32431607, 2020). "NLRP1 gain-of-function mutations have been demonstrated to contribute to constitutive inflammasome activation and IL-1β signaling in skin inflammation and cancer development." (PMID 33396632, 2020). "Recent studies have reported that the IL-1β/IL-1R1 signaling pathway promotes cancer proliferation, invasion and metastasis in several cancers." (PMID 32206125, 2020). "Inhibition of IL-1β/IL-1R1 signaling by Anakinra treatment significantly inhibited cancer proliferation and metastasis 27-29." (PMID 32206125, 2020). "Meanwhile, knockdown of IL-1β was shown to limit the capability of cancer cells to colonize the lungs, demonstrating that IL-1β is needed for lung metastasis formation and growth." (PMID 33322216, 2020). "The interaction between B-cells and cancer cells allows IL-1β secretion, which is responsible for renal cancer cell migration, through HIF-2α and Notch1 pathways." (PMID 32635472, 2020). "Targeting IL-1β with canakinumab as part of the CANTOS study revealed decreased incidence of lung cancer as well as lower cancer mortality compared to the placebo group." (PMID 32883606, 2020). "On the other hand, at the metastatic site, IL-1β maintains cancer cells in a ZEB1-positive differentiation state, preventing their establishment." (PMID 32635472, 2020). "In mice, induction of oral malignancy by 4-Nitroquinolin-1-oxide (4-NQO) and arecoline triggers pro-IL-1β expression, which is proportional to cancer severity." (PMID 32635472, 2020). "Pizato and colleagues demonstrated that DHA induced pyroptosis-associated markers, such as NF-κB, HMGB1, CASP-1, GSDMD, and IL-1β, resulting in cancer cell death." (PMID 33014808, 2020).
cancer (continued). "In colorectal cancer, the combined use of a TGF-β-activated kinase 1 (TAK1) inhibitor plus a TGFBR1 inhibitor avoid the IL-1β and TGF-β1-mediated conversion of resident fibroblasts into cancer-associated fibroblasts (CAFs)." (PMID 32516941, 2020). "The systemic IL1β levels were generally low with minor variations and undetectable levels in several patients; the detection of low IL1β levels is consistent with previous studies of cancer patients." (PMID 32707675, 2020). "Tumor-specific effector TH1 cells establish a pro-inflammatory tumor microenvironment after tumor infiltration and their ability to mediate anti-cancer immune responses depends on IL-1 signaling, which can be delivered by both IL-1α and IL-1β." (PMID 33584721, 2020). "IL-18 induces programmed cell death protein 1-dependent immunosuppression in cancer, and IL-1β is one of the most important pro-inflammatory mediators involved in immune resistance." (PMID 33096896, 2020). "Mechanistically, cancer cells secret interleukin 1β (IL1β) to activate the nuclear factor kappa B (NF-κB)/p65 pathway in SCs, thereby increasing the production of interleukin 6 (IL6) from SCs." (PMID 32308766, 2020). "In recent observations, the anaphylatoxins C3a and C5a seems to significantly contribute to cancer-related inflammation, recruiting myeloid suppressor cells, and promoting IL-1β and IL-17 response in neutrophils, thus enhancing colon carcinogenesis." (PMID 32345771, 2020). "Further, western blot assays showed that caspase-1 and IL-1β expression levels were downregulated in RCC cancer tissues, indicating the same trend." (PMID 32303673, 2020). "Specifically, overexpression of LncRNA ADAMTS9 promoted LDH release, and increased NLRP3 and ASC expression levels in cancer tissues, and promoted IL-18 and IL-1β expressions in mice serum." (PMID 32516127, 2020). "After traversing BBB, cancer cells secrete various cytokines, chemokines, and mediators, particularly IL-1β, TNF-α, IFN-γ, CCL2, CXCL8, and COX2." (PMID 31900168, 2020). "In cancer, IL-1β and S100A9 have been involved in the mobilization of pro-tumoral immature neutrophils with immune suppressive functions." (PMID 32466264, 2020). "Accordingly, in our work, the analysis of CM of co-cultures combined with the total lysates of macrophages and cancer cells, evidenced that macrophages are the main producers of secreted IL-1β." (PMID 32231135, 2020). "In the secretome of patients with advanced carcinoma, it has been possible to find a positive correlation between the secretion of IL-6, IL-1β, IL-2, and IL-4 and the concentration of MGAs." (PMID 32630302, 2020). "IL-1β was shown to promote carcinoma by repressing miR-101 expression through a cyclooxygenase 2 (COX2)/HIF1α pathway." (PMID 32635472, 2020). "The obtained results showed that compound 1, 2, and 3 were capable of lowering NO, TNF-α, and IL-1β release and suppressed the growth and development of human carcinoma cell lines." (PMID 33302335, 2020). "In osteoblastic metastases, osteoblasts produce many factors including insulin-like growth factor 1 (IGF-1), insulin-like growth factor 2 (IGF-2), TGF-β, TNF-α and IL-1β that act as chemoattractants for cancer cells." (PMID 30823602, 2019). "Evidence supporting a pro-tumorigenic role for IL-1β across all cancer types has been accumulating over many years and has been extensively reviewed in recent times." (PMID 31231372, 2019). "It has been shown that in both autocrinal and paracrinal manners, IL-1β stimulates its own production by microenvironment-residing non-cancerous cells; thus promoting the auto-perpetuating inflammatory loop involved in cancer progression." (PMID 31480312, 2019). "Mechanistically, it has been shown in different types of cancer models that IL-1β augments intratumoral immunosuppressive macrophages and increases levels of VEGF and fibroblast growth factor (FGF), supporting angiogenesis and metastasis." (PMID 32039025, 2019).
cancer (continued). "Various inflammatory cytokines from cancer cells, such as IL-1β and TNF-α, activate endothelial cells and promote leukostasis." (PMID 31434194, 2019). "OSCC-derived IL-1β favored stromal glycolysis and induced a lactate shuttle to cancer cells, which facilitated the proliferation of OSCC cells." (PMID 31492049, 2019). "Several members of this family, such as IL-1β and IL-18, have been extensively investigated in cancer with both pro- and anti-tumorigenic functions ascribed to these cytokines." (PMID 31231372, 2019). "The chromosome 9 QTL interval contains several genes involved in inflammation and/or in cancer such as Caspase 1 (Casp1) and pannexin 1 (Panx1), involved in the release of mature inflammatory IL-1β." (PMID 31049358, 2019). "In that setting, interleukin 1 beta IL1B released by macrophages signals via the interleukin 1 receptor type 1 (IL1R1) on the cancer cells to maintain high expression of ZEB1." (PMID 31623163, 2019). "Collectively, our findings highlight the potent adjuvant activity of IL-1β in ACT for cancer treatment and delineate how inflammation shapes the host environment to modulate T cell responses." (PMID 31405895, 2019). "IL-1β production contributes to cancer development and progression but also limits the 5-FU anticancer effect through NLRP3 inflammasome activation in MDSC7,28–30." (PMID 31217433, 2019). "The same test was used for IL-1β where an increased risk of 2.5 (95% CI 1-26.23) was calculated for progression from LSIL to cancer, when the IL-1β mRNA expression decreased." (PMID 31554368, 2019). "At the same time, IL-1β can also induce chronic inflammation and activate blood endothelial cells, thereby promoting the metastasis and invasiveness of cancer cells." (PMID 31832112, 2019). "In short, the OS and DFS results show that high NLRP3 inflammasome expression (NLRP3/IL-18/ IL-1β/ASC) in LSCC cancer tissues forecasts a poor outcome compared to low NLRP3 inflammasome expression (NLRP3/IL-18/IL-1β/ASC) in cancer tissues (P < 0.05)." (PMID 31312615, 2019). "In contrast, IL-1β mRNA ISH signal was limited to stromal cells in focal areas close to cancer cell de-differentiation and budding." (PMID 30999696, 2019). "A growing number of studies have proven the regulatory roles of inflammasome-dependent cytokines (IL-1β and IL-18) in cancer development." (PMID 31492049, 2019). "In particular, ATC shows increased expression of several proinflammatory cytokines (especially of IL-1β) that, via a feedforward autocrine loop, promotes cell invasion in this cancer type." (PMID 31174324, 2019). "Given the pro-tumoural effect of IL-1β, it would be reasonable to test blockade of IL-1 receptor signalling in cancer cells as a possible treatment for PDAC." (PMID 31588122, 2019). "Despite benefiting the type 1 immune response, IL-1β often exerts adverse effects in the context of cancer." (PMID 32039025, 2019). "Consistently, the most important inflammatory cytokines—TNF-α, IL-1β and IL-6—can all be used by cancer cells to induce osteoclastogenesis by activating the NFkB pathway." (PMID 30641973, 2019). "Impressively, the SCNE dramatically depressed key circulating pro-cancer inflammatory cytokines (IFNγ, TNFα, IL-6, IL-1α, and IL-1β) in all of the xenograft and 4NQO-1 mouse models tested." (PMID 31572681, 2019). "IL1β then acts as a pro-proliferative factor, enhancing proliferation of both ER+ cancer cells and fibroblasts." (PMID 31419632, 2019). "Cancer cell contact with the ECM: IL-1β expression and exposure of submesothelial collagen, blood vessels, and sequestered VEGF/TGF-β1 enhance cancer cell adhesion and invasion, particularly at peritoneal stomata/omental milky spots." (PMID 31198853, 2019). "It is clear, therefore, that these dichotomous findings regarding IL-1β need to be carefully considered when developing anti-cancer therapies designed to inhibit IL-1β." (PMID 31231372, 2019).
cancer (continued). "More patients (4/14; 28.6%) with late stages of cancer were in the low IL-1β-serum-level group than those (2/10, 20%) in the high IL-1β-serum-level group." (PMID 31816951, 2019). "The different results in the IL-1β relationship obtained from the development of different types of cancer, leads us to believe that the reduction in IL-1β expression is a protective factor for the development of cancer." (PMID 31554368, 2019). "Together, these findings are the first to identify the activation of signaling processes by IL-1β, leading to the acquisition of resistance to cisplatin in cancer cells." (PMID 30641908, 2019). "Co-culture of macrophages and cancer cells results in an initial switch to a phenotype characterized by high expression of IL-1β and IL-10, while an MRC1 expression remains unmodified." (PMID 31697737, 2019). "High expression levels of NLRP3 in microglia and the contribution of IL-1β in the development and progression of malignant tumors create new interesting directions for future cancer studies." (PMID 31231208, 2019). "IL-1β activates the NF-κB signaling pathway of myeloid cell lines (MDSCs), and NF-κB is an important link between inflammation and cancer." (PMID 31832112, 2019). "Leptin indirectly affects prostate cancer cell growth via promoting bone resorption, and increased expression of IL-1β drives cancer cell colonization of BMA in breast cancer." (PMID 31334678, 2019). "Although rIL1β induced proliferation of both the cancer cells and fibroblasts, IL1β target genes were significantly upregulated in the NAFs, but not in MCF7." (PMID 31419632, 2019). "IL-1β increases inflammatory signaling and enhances epithelial-mesenchymal transition in cancer cells through the IL-1β/HIF-1α/COX2 axis, which promotes the invasive capacities of tumoral cells in a hypoxic microenvironment." (PMID 31507607, 2019). "Recently, it was reported that IL-1β regulates cell proliferation through stemness markers such as Bmi-1, Lgr-5, c-myc and Nanog in cancer stem cells." (PMID 31671670, 2019). "Although there are inherent problems with IL‐1R blockade, inhibition of IL‐1β has shown promising results in animal models of several cancers." (PMID 30191960, 2019). "To investigate the mechanism by which IgG amplifies IL-1β production induced by cancer cell debris in M2 polarised macrophages, we blocked the Fc gamma receptors (FcγR) using anti-CD16, anti-CD32a, anti-CD32b, and anti-CD64 antibodies." (PMID 31588122, 2019). "Chronic incidence of TNF-α and IL-1β in tumors stimulate pro-tumoral effects in several cancers, showing that these two cytokines are potential targets for cancer therapy." (PMID 31665136, 2019). "IL-1α and IL-1β are amongst the most prominent and potent inflammatory cytokines, together with TGFβ, TNFα, and IL-6, in the TME, and are implicated in cancer-related inflammation." (PMID 31557902, 2019). "In a NSCLC cancer study of patients treated with radiotherapy, increased levels of IL-1β showed a direct correlation with worse overall survival compared to patients with lower levels." (PMID 32039025, 2019). "Patients with malignancies (Group 1) showed increased IL-1β, IL-6, and IL-8 as well as decreased numbers of CD163+ M2 macrophages." (PMID 31366164, 2019). "Previous in vitro studies have indicated that RA treatment increased the production of some inflammatory cytokines such as IL-1β by cancer cells." (PMID 30764845, 2019). "Infections by P. gingivalis and F. nucleatum have been proven to cause cancer through pathways of MMP9 and upregulation of cytokines such as TNF-α, IL-1β, and IL-6." (PMID 31297102, 2019). "We examined the role of IL-1β in Salmonella-mediated cancer therapy by blocking its activity with an anti-IL-1β antibody." (PMID 31754923, 2019). "The latest literature reports that ΔppGpp S. typhimurium exerts anti-cancer effects by promoting secretion of IL-1β from macrophages or dendritic cells." (PMID 31754923, 2019).
cancer (continued). "IL1β also induces cyclooxygenase-2, hypoxia-inducible factor 1α which promotes angiogenesis, inflammation, and metastasis in cancer." (PMID 31398937, 2019). "Our study reveals that secretome of cocultured UC-MSCs apparently enhances stem cell-like characteristics of cancer cells, which is dependent on IL-1β secretion of inflammatory UC-MSCs." (PMID 29670904, 2018). "The inhibition of IL-1β signaling was reported to block the development of inflammatory, neuropathic, and cancer pain." (PMID 30442166, 2018). "The results of this review show that açaí acts in the inflammatory processes involved in induced-cancer in animals by decreasing the levels of IL-1β, IL-5, IL-6, IL-8, COX-2, TNF-α and MPO and increasing the levels of IFN-γ." (PMID 29966007, 2018). "We show how KRAS-mutant cancer cells utilize myeloid-IL-1β in order to activate IKKα and alternative NF-κB signaling and to by-pass IKKβ canonical NF-κB dependence." (PMID 29445180, 2018). "Keap-1 knocked-down amplified M2-macrophages induction by cancer cells, appearing as decreased IL-1b and IL-6 expression, and increased CD163 and Arg1 expression." (PMID 30180849, 2018). "Immunofluorescence analysis of lungs of NSG mice injected with MDA-MB-231 cells showed that cancer cells surrounded by macrophages express IL1α and IL1β as early as 5 days post injection." (PMID 29777109, 2018). "For example, increased levels of IL-1β and IL-1ra have been observed in bronchoalveolar lavage of smokers, whereas their levels were decreased in cancer patients who smoke." (PMID 30052665, 2018). "The IL-1B-driven detrimental role of the inflammasome in cancer opposes to its protective role, mainly driven by IL-18, as reviewed in." (PMID 29760166, 2018). "High CDH1 and low IL-1B in cancer cells induce MSC organization into a niche like formation, dependent on direct cell–cell contact, in vitro." (PMID 29760166, 2018). "Our data demonstrate that NF-κB inhibition can block the acidic bile-induced overexpression of TNF-α, NF-κB transcriptional factor RELA(p65), and cancer related cytokines, IL-1β and IL-6." (PMID 29464041, 2018). "IL-1B signalling and inflammation are strongly connected and inflammation plays a major role during cancer progression." (PMID 29760166, 2018). "Cancer cells themselves aberrantly produce these molecules, including IL-1β, and surrounding stromal cell and immune cells also significantly contribute to elevated expression levels." (PMID 30048474, 2018). "Taken together, upon coculturing with cancer cells, UC-MSCs obtain inflammatory phenotype with enhanced secretion of IL-1β." (PMID 29670904, 2018). "When treated with IL-1B, MSCs were found to upregulate the same cytokines that were observed following exposure to cancer cell conditioned media." (PMID 29760166, 2018). "Clinically, a correlation between high levels of IL-1β and bad prognosis in cancer patients was observed." (PMID 30042333, 2018). "After 2 days of co-culture, monocytes exposed to cancer cell lines showed markedly upregulated expression of M1-associated (TNF-α, IL-1β), M2-associated (CCL13, CD206), Mreg-associated (IL-10, TGF-β), and angiogenesis associated (MMP9, VEGF) genes." (PMID 29668679, 2018). "IL-1β binds to its receptor and activates NF-κB that initiates JNK signalling causing proliferation, invasion and cancer development." (PMID 30447690, 2018). "To confirm the role of inflammatory signals in M1-induced EMT, we neutralized IL-6, IL-1β, and TNFα in M1-treated A549 cancer cells and examined the expression of EMT markers." (PMID 30218063, 2018). "It is well known that IL-1β is an important proinflammatory cytokine that promotes growth, invasiveness, and metastasis of a variety cancer cells." (PMID 30211233, 2018). "Our results indicate that cancer cell lines significantly upregulated genes associated with M1 monocytes including PDL1, TNF-α, IL-1β, IL-6, IL-8, CCL3, and prostaglandin-endoperoxidase synthase 2 (PTGS2)." (PMID 29668679, 2018).